RB1 (RB transcriptional corepressor 1)
Diseases named in the same sentence as RB1 in open-access papers (continued):
Sharing a sentence is not in itself a finding about the gene and the disease.
myeloma (17 papers, 2011 to 2026). "In conclusion, we have shown that bi-allelic inactivation is more prevalent at relapse in multiple myeloma and that homozygous loss of RB1 is an independent prognostic marker." (PMID 28234347, 2017). "Further investigation of CDKN2C and RB1 mutation, deletion and expression are required to more fully understand the interplay between disruption of these genes and cell cycle control in myeloma." (PMID 28234347, 2017). "Existing research suggests that the deletion of RB1 disrupts the downregulation of IL-6 by its gene product, pRB, leading to elevated IL-6 levels and the subsequent malignant proliferation of myeloma cells." (PMID 39664374, 2024). "In contrast to RB1, the exosome endoribonuclease DIS3 is mutated in ~10% of NDMM and ~75% of these mutations occur in del(13q) myeloma suggesting biallelic loss of DIS3 occurs in most DIS3 mutated myeloma." (PMID 31231360, 2019). "If CKS1B and RB1 are the myeloma-inducing genetic alterations on amp(1q) and del(13q), respectively, questions remain as to why two alterations are needed in the same pathway in addition to overexpression of a Cyclin D gene." (PMID 31231360, 2019). "Furthermore, RB1 deletion likely influences the proliferation of myeloma cells through pRB-mediated cell cycle regulation." (PMID 39664374, 2024). "Bone marrow biopsy with immunohistochemistry confirmed a plasma-cell neoplasm, while myeloma fluorescence in situ hybridization (FISH) revealed 1q21 gain/amplification together with chromosome 13-related abnormalities, including RB1 deletion and D13S319 abnormality." (PMID 42100385, 2026). "Our data imply that the effects of CDK6 in multiple myeloma depend on its kinase function but are independent of RB1, the CDK4/6 substrate which is most relevant for other cancers." (PMID 35197447, 2022). "Furthermore, frequent homozygous deletions of genes playing important role in myeloma biology such as TRAF3, BIRC1/BIRC2, RB1, or CDKN2C were observed." (PMID 24987674, 2014).
carcinoids (16 papers, 2012 to 2025). "Based on our results, carcinoids seem to use the signaling cascade via upregulation of CDK4/6 and CCND1 expression to control RB1 phosphorylation." (PMID 26008974, 2015). "Carcinoids have increased CDK4/6 and CCND1 expression controlling RB1 phosphorylation via this signaling cascade." (PMID 26008974, 2015).
head and neck squamous cell carcinoma (16 papers, 2004 to 2024). A squamous cell carcinoma that arises from any of the following anatomic sites: lip and oral cavity, nasal cavity, paranasal sinuses, pharynx, larynx, and salivary glands. "Disrupted Rb pathway (loss of expression of RB1 and/or of CDKN2A) in 55.9% of analysed cases confirmed the hypothesis that RB1 pathway is altered in head and neck squamous cell carcinomas, with CDKN2A (45%), rather than RB1 (11.8%) being more frequently inactivated." (PMID 15083191, 2004).
pituitary tumor (16 papers, 1998 to 2025). A benign or malignant neoplasm affecting the pituitary gland. "Loss of Rb expression was reported in some human pituitary tumors, which was related to RB1 gene promoter methylation." (PMID 40257628, 2025). "This is an important observation as Rb1+/-; Cdkn1a-/- mice are susceptible to pituitary tumors and have similar survival as for Rb1G/+; Cdkn1b-/- animals, this indicates that the Rb1G mutation cooperates preferentially with p27 loss." (PMID 30703085, 2019). "The previously reported earlier onset of pituitary tumours in cross-bred mice inheriting a mutant Rb-1 allele paternally has been ascribed to imprinting of an Rb-1-linked gene." (PMID 9716031, 1998). "In conjunction with prior results that Rb1G/G; Cdkn1b-/- animals succumb to pituitary tumors, and that Rb1+/-; Cdkn1a-/- mice have accelerated pituitary tumorigenesis, these genetic crosses provide two simple conclusions relating to RB function in cell cycle and cancer susceptibility." (PMID 30703085, 2019). "Rb1 mouse models develop highly penetrant pituitary tumors—ACTH-secreting tumors in most cases, evidence that supports RB pathway playing a role in pituitary tumorigenesis." (PMID 32733644, 2020). "Based on the longitudinal imaging data acquired by MRI, eRapa appears to inhibit Rb1−/− pituitary tumor development and growth in Rb1+/− mice, which is likely a major factor in its ability to extend lifespan in this model." (PMID 23454836, 2013). "RB1 gene is involved in cell proliferation and apoptosis and was studied in pituitary tumors." (PMID 30781725, 2019). "In addition, these mice are highly cancer prone and succumb to pituitary tumors as seen in Rb1+/- mice." (PMID 30703085, 2019). "Based on their influence on TFs promoting cell cycle progression, both p16 and pRb may aptly be viewed as “cell cycle brakes” that carefully regulate cell proliferation, as demonstrated by the fact that 100% of Rb1 transgenic knockout mice develop pituitary tumors." (PMID 24367530, 2013).
eye cancer (15 papers, 2012 to 2025). "A mutation of the retinoblastoma (RB1) gene can cause cancer of the eye in infants, but also increases the risk of BC." (PMID 41018918, 2025). "Rb is an inherently “genetic” form of ocular cancer, and all patients with bilateral Rb and 10–15% of patients with unilateral Rb have germline RB1 mutations." (PMID 39234041, 2024). "Complex DNA rearrangements such as RB1 gene deletions have also been observed in patients with RB and other non-ocular cancers, resulting in loss of function of the RB1 protein and cell cycle dysregulation." (PMID 31835688, 2019).
hereditary retinoblastoma (15 papers, 2003 to 2025). An autosomal dominant disorder caused by pathogenic variants in the RB1 gene, characterized by an increased risk of retinoblastoma in early childhood. "For instance, Hereditary Breast and Ovarian Cancer (HBOC) is associated with mutations in BRCA1/2, Von Hippel-Lindau (VHL) syndrome is associated with mutations in the VHL gene, and Hereditary Retinoblastoma is associated with mutations in the RB1 gene." (PMID 40695959, 2025). "For example, RB1, which is associated with hereditary retinoblastoma, was endorsed for screening by 50 of 56 experts (89.3%)." (PMID 37155167, 2023). "Hereditary retinoblastoma arises from an autosomal dominant mutation in the RB1 tumor-suppressor gene for Rb cell cycle regulator." (PMID 35267600, 2022). "Hereditary retinoblastoma and hereditary renal cell carcinoma (Von-Hippel Lindau disease) arise with the inheritance of a germline loss-of-function mutation in Rb1 and VHL, respectively." (PMID 32295625, 2020). "Patients treated for hereditary retinoblastoma are at an increased risk of developing non-ocular malignancies due to a mutation in the second RB1 allele in different tissues." (PMID 16934146, 2006).
pancreatic NET (14 papers, 2018 to 2025). "It has been reported that pancreatic NET patients with retinoblastoma 1 (RB1) deletion and Kirsten rat sarcoma virus (KRAS) mutations exhibited a better treatment effect with platinum-based chemotherapy." (PMID 35752613, 2022). "RABL6A is an oncogenic, RAB-like GTPase previously shown to inhibit RB1 signaling in pancreatic neuroendocrine tumors via downregulation of p27." (PMID 33456709, 2021).
bladder tumors (13 papers, 2012 to 2025). "At the 25th week of gestation, she underwent transurethral resection of the bladder tumor, and the pathological diagnosis was bladder leiomyosarcoma with loss of RB1 expression." (PMID 37491255, 2023). "Genetic alterations that frequently occur in bladder tumors, for example, Rb1 loss and c-myc amplification, also drive EZH2 expression and activity." (PMID 30692641, 2019). "RB1 mutations are rarely seen in low grade or low stage bladder tumors." (PMID 26039708, 2015). "Therefore, patients who can potentially benefit from EZH2 inhibition would include those whose bladder tumors possess KDM6A and SWI/SNF mutations, Rb1/c-myc alterations and post-translational modifications of EZH2." (PMID 30692641, 2019). "However, this patient did not present an RB1 mutation in their primary bladder tumor; however, they did in their metastatic tissue." (PMID 38098507, 2023).
head and neck cancer (13 papers, 2011 to 2026). A primary or metastatic malignant neoplasm affecting the head and neck. "Previous in vitro research on head and neck cancer found 16.6% cytosine methylation in the CpG dinucleotides of the retinoblastoma 1 (RB1) gene, which is an important cell cycle regulator." (PMID 36765652, 2023). "RB1 is mutated in 6–24% of HPV-positive head and neck cancers, a similar fraction to HPV-negative head and neck cancers (4%)." (PMID 28771191, 2017). "In HPV-positive head and neck cancers, significant copy number losses have been reported in 22 genes and gains in 65 genes, including RB transcriptional corepressor 1 (RB1) and PIK3CA." (PMID 28771191, 2017). "Although not significant, RB1 overexpression was found in head and neck carcinomas." (PMID 28751665, 2017).
diabetes (12 papers, 2015 to 2024). "Researchers found that Rb1 can alter the amino acids associated with diabetes, such as branched-chain amino acids, tryptophan, and alanine." (PMID 37049846, 2023). "This study determined the underlying mechanisms of Rb1 treatment that acted on diabetes-injured lungs in diabetic rats." (PMID 36367996, 2022). "This study was to investigate the effect of Rb1 on diabetes injured cardiac muscle tissue and to further investigate its possible molecular pharmacology mechanisms." (PMID 38961333, 2024). "We found that although total RyR2 remained significantly unchanged, phosphorylation of RyR2 at Ser2808 increased significantly during diabetes, and these increases were attenuated by insulin and Rb1 treatment." (PMID 38961333, 2024). "We also found that at equivalent amounts of RyR2 protein from diabetes rats, the heart bound less [3H] ryanodine activity compared with control rats; insulin and Rb1 treatment increased the [3H] ryanodine activity." (PMID 38961333, 2024). "Diabetes increased the apoptosis rate (2.23-fold vs. control), and Rb1 treatment decreased the apoptosis rate (1.73-fold vs. the diabetic rats)." (PMID 36367996, 2022). "The increasing IL-6, IL-1α, TNF-α and TGF-β expression in the lungs of diabetic rats indicates that the expression of proinflammatory cytokines was upregulated in diabetes and was downregulated by insulin and Rb1 treatment." (PMID 36367996, 2022). "Based on this, we investigated the protective role of Rb1 in EC injury and atherosclerotic plaque formation in the context of diabetes." (PMID 36163178, 2022). "In line with this, specific deletion of endothelial Nrf2 and PGC-1α attenuated the protective effects of Rb1 on the development of arteriosclerotic plaque and aortic oxidative stress/inflammation in mice with diabetes-accelerated atherosclerosis." (PMID 36163178, 2022). "This study demonstrated that synergistic regulation of Keap1 and p47phox by Rb1 contributes to Nrf2 activation in ECs, thus protecting against endothelial dysfunction and diabetes-accelerated atherosclerosis." (PMID 36163178, 2022). "Our findings have shown the effect and possible mechanism of Rb1 in treatment for diabetic macroangiopathy and diabetes-related complications prevention." (PMID 34712140, 2021). "Diabetes increased the apoptosis rate, and Rb1 treatment decreased the apoptosis rate." (PMID 38961333, 2024). "This study provides further evidence that Rb1 could be developed as a therapeutic target for ED in diabetes." (PMID 37765046, 2023). "Overall, we demonstrated that blockade of ROS overproduction by Rb1 could prevent diabetes-accelerated atherosclerosis." (PMID 36163178, 2022). "Collectively, we demonstrated that Rb1, which directly targeted Keap1 and p47phox in ECs, may be an attractive candidate for the treatment of atherosclerosis in diabetes." (PMID 36163178, 2022). "Conclusion and Implications: Rb1 may represent a novel prevention strategy to alleviate collagen deposition and degradation to prevent diabetic macroangiopathy and diabetes-related complications." (PMID 34712140, 2021). "The aim of this study was to explore whether Rb1 could alleviate the pathophysiological process of arterial stiffening in diabetes and its potential mechanisms." (PMID 34712140, 2021). "The mechanism for Rb1 protecting the myocardia of diabetic rats is reducing or scavenging ROS, RCS production, and RyR2 phosphorylation in diabetes mellitus." (PMID 38961333, 2024).